SLC49A3 (solute carrier family 49 member 3)
Synonyms: MFSD7; LP2561; FLJ22269
Tractability: Antibody: UniProt predicts a signal peptide or a membrane-spanning region.
Gene: Protein-coding gene on chromosome 4 (681,824 to 689,396, reverse strand). Ensembl gene ENSG00000169026.
Subcellular location: Membrane
Gene Ontology:
Molecular function: transmembrane transporter activity
Biological process: transmembrane transport
Cellular component: membrane
Genetic constraint (gnomAD): Loss-of-function variants: 50 observed, 43.83 expected, observed/expected ratio (o/e) 1.14, 90% interval 0.91 to 1.44. The synonymous counts are far from expectation, so gnomAD's model fits this gene poorly and the ratio says little. Missense variants: 906 observed, 687.47 expected, observed/expected ratio (o/e) 1.32, 90% interval 1.25 to 1.39. Synonymous variants: 413 observed, 306.67 expected, observed/expected ratio (o/e) 1.35, 90% interval 1.24 to 1.46.
Homologues: Orthologues: chimpanzee SLC49A3 (98% identical), macaque SLC49A3 (65% identical), rat Slc49a3 (64% identical), mouse Slc49a3 (63% identical), guinea pig SLC49A3 (62% identical), pig SLC49A3 (59% identical), dog SLC49A3 (54% identical), tropical clawed frog slc49a3 (38% identical), Caenorhabditis elegans B0416.5 (28% identical), Caenorhabditis elegans C05G5.1 (25% identical), Caenorhabditis elegans C42C1.8 (24% identical). Paralogues in human: FLVCR1 (22% identical), SLC49A4 (20% identical), FLVCR2 (19% identical), CFAP276 (4% identical).
Diseases named in the same sentence as SLC49A3 in open-access papers:
SLC49A3 is named in the same sentence as 3 diseases in open-access papers, as found by Europe PMC text mining. Sharing a sentence is not in itself a finding about the gene and the disease. The quoted sentences say what the papers report.
ovarian carcinoma (2 papers, 2010 to 2023). A malignant neoplasm originating from the surface ovarian epithelium. "SLC49A3 is known as major facilitator superfamily domain containing 7 (MFSD7), which is associated with risk of ovarian cancer, although its functional characteristics are mostly unknown." (PMID 36456177, 2023).
SLC49A3 also shares sentences with these, for which no sentence is quoted: cancer (1 paper); infection (1).